SIRT6 (sirtuin 6)
Diseases named in the same sentence as SIRT6 in open-access papers (continued):
Sharing a sentence is not in itself a finding about the gene and the disease.
cancer (continued). "SIRT6 and SIRT7 were mainly expressed in cancer cells, enterocytes, MSCs, and goblet cells, when SIRT7 also expressed in PMCs and neck-like cells." (PMID 36324577, 2022). "We observed that SIRT6 induces ERK1/2‐dependent mitochondrial fission, which, in turn, can regulate cancer cell invasion and migration." (PMID 35686673, 2022). "SIRT6 is regulated by deacetylation nicotinamide phosphoribosyltransferase (NAMPT) activity and restores NAD(P)(H) pools in cancer cells." (PMID 33440786, 2021). "Our study indicates SIRT6 as a new, potentially druggable target to be exploited for interfering with OXPHOS in BC, thereby achieving cancer-preventive but also, possibly, therapeutic effects." (PMID 33482921, 2021). "The mammalian SIRT6 protein, a member of the Class III HDAC Sirtuin family of NAD+-dependent enzymes, plays pivotal roles in aging, metabolism, and cancer biology." (PMID 34573442, 2021). "Here, we have characterized a functional interaction between SIRT6 and ACLY which plays essential roles in modulating nuclear acetyl-CoA abundance, locus-specific histone acetylation, and the expression of cancer cell adhesion and migration genes." (PMID 34573442, 2021). "Sirtuin 6 (SIRT6), a member of sirtuin family (SIRT1–7), regulates a variety of cellular processes involved in aging, metabolism, and cancer." (PMID 33684691, 2021). "Cell-based studies revealed that UBCS039 activates SIRT6 and decreased H3K9 and H3K56 acetylation levels in various cancer cell lines such as NSCLC, fibrosarcoma, colon and epithelial cervix carcinoma." (PMID 33800266, 2021). "Therefore, both blocking CSNK2A1 and SIRT6 or the direct suppression of the DNA damage repair pathway might be promising therapeutic strategies to overcome cancer resistance to conventional genotoxic anti-cancer therapeutics." (PMID 34359939, 2021). "CSNK2A1 serves cancer progression by inducing the phosphorylation of various molecules, including SIRT1, SIRT6, and CCAR2." (PMID 34359939, 2021). "In 72 paired KIRC tissues and corresponding adjacent normal tissues, expressions of SIRT4 and SIRT5 were down-regulated in cancer tissues than in normal tissues, while expressions of SIRT6 and SIRT7 were up-regulated in cancer tissues." (PMID 32158696, 2020). "SIRT6 activators have been developed, and UBCS039 (a specific SIRT6 activator) has shown promising results in a human cancer cell line where it triggered autophagy." (PMID 32937960, 2020). "SIRT6, which belongs to the sirtuin family, is an NAD+‐dependent deacetylase that plays a pivotal role in human cancers by targeting a variety of proteins." (PMID 33037850, 2020). "Sirtuin 6 (SIRT6), a member of the sirtuin family, is NAD+-dependent deacetylases with important roles in glucose homeostasis, maintenance of genome stability and cancers development." (PMID 31842909, 2019). "SIRT6 and SIRT7 are both nuclear proteins with deacetylase activity and function as both tumor suppressor and promotor in cancer, including OC." (PMID 31572453, 2019). "Sirt6 has at least two same targets H3K56 and H3K9 from previous study and has similar effect in many biological processes like aging and cancer." (PMID 30630525, 2019). "Like SIRT1, SIRT6 is also able to reduce the transcription of MYC and HIF-1 in cancer cells by reprogramming glucose metabolism." (PMID 30761005, 2019). "SIRT6 is an NAD+-dependent deacetylase with a role in regulation of DNA repair, telomere maintenance, glucose and lipid metabolism, inflammation, and cancer." (PMID 31708789, 2019). "Our study also reports the cellular consequences of autophagy induction by the pharmacological activation of SIRT6, demonstrating that UBCS039 limits the growth of several cancer cell lines by eliciting apoptosis." (PMID 30250025, 2018).
cancer (continued). "Here we demonstrate that a newly synthesized SIRT6 activator, the pyrrolo[1,2-a]quinoxaline derivative UBCS039, is effective in triggering autophagy in several human cancer cell lines of different histotypes." (PMID 30250025, 2018). "Sirtuin 6 (SIRT6) is a member of the NAD+-dependent class III deacetylase sirtuin family, which plays a key role in cancer by controlling transcription, genome stability, telomere integrity, DNA repair, and autophagy." (PMID 30250025, 2018). "SIRT6 acts as a co-repressor of HIF-1α and subsequently inhibits aerobic glycolysis in cancer cells." (PMID 27659520, 2017). "SIRT6 expression was lower in cirrhotic and HCC tissues than in normal liver tissues according to a publically available cancer microarray dataset." (PMID 27824900, 2016). "Thus SIRT6 might have distinct functions depending on the type of cancer." (PMID 26426055, 2015). "In conclusion, our findings provide compelling evidence that SIRT6 establishes a network linking nuclear and mitochondrial transcription through the regulation of TFAM, identifying TFAM as a potential therapeutic target for cancer." (PMID 41362737, 2026). "Beyond cancer, a similar context-dependent metabolic switch orchestrated by SIRT6 is observed in non-malignant pathologies." (PMID 41463311, 2025). "Unlike sirtuins with narrow metabolic roles, SIRT6 exerts broad control over glycolysis, oxidative phosphorylation, and lactate secretion, which links its activity to both cancer metabolism and systemic metabolic diseases." (PMID 41463311, 2025). "Histone deacetylases, including sirtuin 6 (SIRT6) and histone deacetylase 11 (HDAC11), can promote glycolysis by suppressing the expression of intermediate signaling molecules, which in turn contributes to targeted therapy resistance in cancer cells." (PMID 40919131, 2025). "Specifically, SIRT6 induces MDM2-mediated degradation of SIRT1, thereby relieving the protective role of SIRT1 and allowing accumulation of reactive oxygen species (ROS), which ultimately drive cancer cell death." (PMID 41463311, 2025). "Moreover, 6a can increase SIRT6 activity, reduce acetylation of H3K9/K56 and stimulate autophagy‐driven apoptosis in different cancer cells, including fibrosarcoma, epithelial cervix carcinoma, CRC, and NSCLC." (PMID 39215785, 2025). "SIRT6, an NAD + -dependent deacetylase, regulates diverse biological processes, including DNA repair, the oxidative stress response, and lipid metabolism homeostasis, and has dual roles in cancer development and progression." (PMID 41354870, 2025). "Sirtuin 6 (SIRT6) is a mammalian homolog of the yeast deacetylase, Sir2 (Silent Information Regulator-2), which regulates fundamental processes in lifespan control, metabolism, and cancer biology." (PMID 39955062, 2025). "SIRT6 suppresses the transcription of Serpina12 through histone H3K9 deacetylation at its promoter, thereby reducing glucose uptake, lactate production, and aberrant lipid synthesis, ultimately limiting cancer cell proliferation and survival." (PMID 41463311, 2025). "We first challenged Sirt6 Floxed and LKO mice with diethylnitrosamine (DEN), a proven liver carcinogen, on postnatal day 14 and examined cancer formation when mice reached 7 months of age." (PMID 38332150, 2024). "Finally, the identification of protein interaction networks involving SIRT6, particularly within the PIN7 network, emphasizes its role in age-related diseases and cancer." (PMID 39796040, 2024). "Considering that MZF1 and SIRT6 were differently expressed in NSCLC cell lines and normal lung epithelial cell lines and that the function of SIRT6 in cancers remains controversial, we first tried to elucidate the function of MZF1 and SIRT6 in A549 and H460 cells." (PMID 39224032, 2024). "Furthermore, SIRT6 inhibits the IGF/AKT pathway, which is responsible for suppressing autophagy, while activating the PI3K/AKT/mTOR pathway, which promotes cancer progression." (PMID 37175631, 2023).
cancer (continued). "Moreover, SIRT6 suppresses the JAK2/STAT3 signaling pathway, which typically becomes activated in the progression of various cancers." (PMID 37175631, 2023). "Compared to SIRT6/7, SIRT2 promotes cancer metabolism through stabilizing MYC." (PMID 35935878, 2022). "Finally, the fibronectin adhesion assay was used to assay effects of SIRT6 and ACLY on cell adhesion to the extracellular matrix (ECM), which contributes to cancer cell invasiveness." (PMID 34573442, 2021). "Following exposure to UV-B radiation, the activation of AKT pathway induces an increase of SIRT6 levels which promotes COX-2 expression through repression of AMP-activated protein kinase (AMPK) signaling, finally leading to cancer cell survival and proliferation." (PMID 33800266, 2021). "Following genotoxic stress, SIRT6 is recruited to DNA damage sites where it activates through deacetylation DNA-PKcs and CtIP, constitutively acetylated in AML cells, consequently promoting DNA repair which in turn supports cancer cell survival." (PMID 33800266, 2021). "In this setting, SIRT6 activates the PI3K/AKT/mTOR pathway, thus facilitating cancer progression." (PMID 33800266, 2021). "Sirt6 also influences MDM2 to suppress Sirt1 activity, thereby also promoting cancer cell death." (PMID 33727672, 2021). "Cancer incidence was similar between genotypes at the time of natural death, and non-significantly lower in SIRT6 and SIRT1 + 6-tg mice at 25 months of age." (PMID 34050173, 2021). "The lysine acetylation regulators with CNV amplification showed significantly higher expression in cancer cells when compared to normal cells (e.g. KAT2A and ATAT1), while the regulators with CNV deletion showed significantly lower expression (e.g. SIRT6 and SIRT7)." (PMID 34136387, 2021). "Considering the role of CSNK2A1 in cancer progression and the phosphorylation of SIRT6 and the role of SIRT6 in chemoresistance through the DNA damage repair pathway, CSNK2A1 and SIRT6 might be involved in resistance to conventional anti-cancer therapies." (PMID 34359939, 2021). "SIRT6 and SIRT7 were up-regulated in 14 of the 15 significantly altered cancer types." (PMID 32158696, 2020). "SIRT5, SIRT6, and SIRT7 exhibited up-regulation in multiple cancer types." (PMID 32158696, 2020). "Consistent with the cooperative action between SIRT1 and SIRT6, independent studies have revealed an interaction between SIRT1 and SIRT7, showing that SIRT1 recruits SIRT7 to promote cancer cell metastasis, and that SIRT1 and SIRT7 antagonistically regulate adipogenesis." (PMID 32538779, 2020). "Our findings also suggest that SIRT1 and SIRT6 also play a coordinate role in fine-tuning FOXO3 acetylation and therefore lapatinib sensitivity by setting a threshold for the de-acetylation activity in both lapatinib sensitive and resistant cancer cells." (PMID 31357743, 2019). "The overexpression of SIRT6 potentiates apoptosis in a series of cancer cell lines, but not in normal, non-transformed cells." (PMID 31591350, 2019). "So far, little is known about the link between SIRT6 and AMPK in cancer." (PMID 30250025, 2018). "For example, deacetylation of nuclear PKM2 by SIRT6 (sirtuin 6) at the K433 residue results in the export of PKM2 to the cytoplasm, thereby restricting its non-glycolytic functions (i.e., transcriptional co-activator and protein kinase) that support cancer." (PMID 29468140, 2018). "In a separate study, we observed that SIRT6 overexpression induces massive apoptosis in cancer cells, but not non-cancerous cells." (PMID 21946623, 2011).
cancer (continued). "SIRT6 concentrations were significantly higher in non‐cachectic cancer patients (3.41 ± 0.30 ng/mL) compared to cachectic cancer patients (3.20 ± 0.23 ng/mL, p < 0.01), suggesting the negative correlation between SIRT6 level and cachexia in patients with cancer." (PMID 39971710, 2025). "As for SIRT6, altered TBX3 levels may play different and opposite roles in cancer." (PMID 38081972, 2023). "Several other computational studies have investigated the effects of EGCG on other cancer-related factors including trypsin, proteasome, PTP1B phosphatase, glutathione S-transferase (GST P1-1), or the epigenetic modulators DNMT, HDAC, and sirtuin-6 (SIRT6), as recently reviewed." (PMID 37446908, 2023). "Targeting the SIRT6/Keap1/Nrf2/GPX4 signaling pathway facilitates ferroptosis in cancer cells, and this property may be may be one of the potential strategies to address the resistance of cancer cells to sorafenib." (PMID 35847022, 2022). "Inactivation of SIRT6 in cancer cells results in the accumulation of nuclear ACLY protein, increasing nuclear acetyl-CoA, which in turn drives site-specific histone acetylation and the expression of cancer cell adhesion and migration genes that promote tumor aggressiveness." (PMID 36171897, 2022). "Notably, a recent study reported that overexpression of SIRT6 thwarts the stem-like traits and tumorigenic capacity of human cancer cells independent of the deacetylase activity." (PMID 31372634, 2019). "SIRT6 overexpression induces massive apoptosis in cancer cells but not in normal cells." (PMID 31817470, 2019). "In other cancer types, such as lung cancer, prostate cancer, melanoma, and non-melanoma skin cancer, SIRT6 is upregulated both at mRNA and protein level, and acts as an oncogene responsible for cancer cell proliferation." (PMID 30761005, 2019). "Sirt6 interacts, deacetylates and affects telomere repeat binding factor 2 (TRF2) stability, which may be part of a higher order complex with functional impacts on DNA damage response (DDR), cancer and aging." (PMID 29535637, 2018). "In addition, several sirtuins including SIRT6 and SIRT7 are found to be critical regulators for cancer cells metabolism and therefore further studies should be implemented to indicate whether the modulation of sirtuins have implications for cancer treatment." (PMID 27659520, 2017). "Similarly, SIRT6 overexpression has been demonstrated to induce apoptosis in cancer cells and not in normal cells." (PMID 28635654, 2017). "However, there is currently no effective drug for cancers related to SIRT6." (PMID 32283646, 2020). "Additionally, the predominantly cytoplasmic localization of SIRT6 expression was correlated with poor prognosis and reduced chemosensitivity in patients with NSCLC, indicating that SIRT6 could be a useful prognostic marker for this type of cancer." (PMID 31591350, 2019). "Sirt1 suppression itself does not lead to cancer cell death, requiring Sirt6- and MDM2-mediated downregulation to induce an anti-cancer effect." (PMID 38254877, 2024). "As yet it is unclear exactly how SIRT6 mono-ADP ribosylation promotes death in cancer cells, but it appears to be independent of PARP1, suggesting that there are additional targets for SIRT6-mediated mono-ADP ribosylation in vivo." (PMID 21946623, 2011). "The absence of SIRT6 leads to hyperacetylation of the Lin28b promoter, Myc recruitment, and significant induction of Lin28b and its downstream let-7 target genes IGF2BP1, IGF2BP3, and HMGA2, thereby promoting the development of cancer." (PMID 35463332, 2022). "Lack of SIRT6 in pancreatic ductal adenocarcinoma (PDAC) determines hyperacetylation of H3K9 and H3K56 at the promoter of the oncogene Lin28b, along with c-Myc recruitment, resulting in the enhancement of cancer progression and metastatization." (PMID 33800266, 2021).
cancer (continued). "Since SIRT6 deacetylase activity has important effects in cells and in cancers, and since NAD+-binding inhibitors block both deacetylation and MARylation reactions, it is not possible to discriminate between the two activities in SIRT6 studies." (PMID 34639169, 2021).